CD4 (CD4 molecule)
Diseases named in the same sentence as CD4 in open-access papers (continued):
Sharing a sentence is not in itself a finding about the gene and the disease.
AIDS (continued). "Using multivariate logistic regression analysis, mortality rate was found to be independently and significantly related to the age of the patient, HIV positive with stigmata of AIDS, CD4 count, inhalation injury, %TBSA and severity of burn (p-value < 0.001)." (PMID 21658212, 2011). "A routine ocular examination should be performed in the AIDS patients with CD4+ T lymphocyte counts less than 50 cells/μl." (PMID 22115120, 2011). "We assume that antiretroviral therapy is given to AIDS individuals who are ill and have experienced AIDS-defining symptoms, or whose CD4+ T cell count is below 200/μL, which is the recommended AIDS defining stage." (PMID 21350680, 2011). "They demonstrated that median HIV-1 RNA explained 51% and 58% of the variability in AIDS and death, and median CD4 count accounted for 29% and 35% of this variability, respectively." (PMID 22194853, 2011). "In conclusion our study shows a high rate of HAART initiation at CD4 cell counts <200 cell/mm3 or with an AIDS-defining illness in Latin-American and the Caribbean, which is substantially below the current cutoff recommended in international guidelines." (PMID 21637802, 2011). "AIDS cases with moderate immunosuppression (225–249 CD4 cells/μL at onset) were estimated to have a 15-fold increased risk of HL." (PMID 21197477, 2011). "The median CD4 count at enrollment was 207 cells/mm3, 66 (62%) had a history of an AIDS-defining opportunistic condition, and 21 (20%) were antiretroviral naïve." (PMID 21324133, 2011). "IRIS is an inflammatory reaction to an opportunistic pathogen and/or tumor antigen that occurs early after initiation of HAART in patients with AIDS and is temporally related to an increase in the host's CD4+ lymphocyte count." (PMID 21791047, 2011). "At baseline, mean age was 48 years, 2% were women, median CD4 count was 106/μl, mean viral load was 4.74 log10 copies/ml, and 59% had a prior AIDS diagnosis." (PMID 21483491, 2011). "Severe herpetic infections are often seen in immunocompromised individuals with impaired CD4+ T cell immunity, such as those with AIDS and transplant patients, which indicate that CD4+ T cells are very important for protection against virus infection." (PMID 21575169, 2011). "Despite the wide availability of cART in Western Europe, access to care with advanced HIV disease remains common in France and Belgium, with almost one third of HIV-infected patients initiating care at CD4 counts <200/mm3 and/or AIDS in recent years." (PMID 21226905, 2011). "In a representative sample of HIV-infected individuals diagnosed between 1996 and 2003 in France, 33.1% of the patients presented to health care facilities with AIDS-defining clinical events or CD4+ T cell counts <200 cells/mm3." (PMID 21283618, 2011). "SIV infection is accompanied by an early depletion of CD4+ T cells in the gut of macaques, and progression to AIDS is characterized by depletion of CD4+ T cells." (PMID 21698207, 2011). "The general importance of CD4+ T cells in human health and immunity was dramatically displayed early in the AIDS epidemic as patients presenting with reduced CD4+ T cell counts developed opportunistic infections." (PMID 21943070, 2011). "Until recently, the World Health Organization (WHO) recommended that all HIV-positive patients with CD4 cell count below 200/mm3 blood or an AIDS-defining illness such as Kaposi's sarcoma should be given ART." (PMID 21949643, 2011). "For instance, in patients with AIDS, a disease with too much apoptosis, the depletion of CD4+ T helper cells has been shown to be mediated by CD95." (PMID 21625619, 2011). "Most ART-naive patients presented with advanced HIV infection or AIDS; 66.7% had a CD4-cell count below 200 cells/mm3, and 62.8% were in WHO stage III/IV." (PMID 21827653, 2011).
AIDS (continued). "Statistical analysis showed a trend that the prevalence of CMV retinitis was significantly difference in the AIDS patients with different levels of the CD4+ T lymphocyte counts (p < 0.001, Cochran-Armitage trend test)." (PMID 22115120, 2011). "This study shows that a high proportion of individuals (55.6%) meet the criteria of the new European definition of LP (CD4 < 350 cells/μl or AIDS)." (PMID 21729332, 2011). "Toxoplasmosis is one of the most common opportunistic brain infections in AIDS, accounting for ≤30% at postmortem studies, particularly when CD4 levels are <300/mm3." (PMID 22187591, 2011). "Initially the WHO clinical staging for HIV/AIDS was used in line with CD4 cut-offs of 200 cells/mm3 to make decisions on ART initiation." (PMID 21589912, 2011). "In summary, results of clinical trials and observational cohort studies have now conclusively demonstrated that earlier initiation of ART ≤350 CD4 cells/mm3 is warranted, to decrease AIDS-related morbidity and mortality." (PMID 21999771, 2011). "Our analysis also identified a clinical AIDS diagnosis preceding HAART as a predictor of a poorer CD4+ response." (PMID 21244701, 2011). "Cases were people living with HIV/AIDS (PLHA) who had a WHO clinical stage of III or IV or a CD4 lymphocyte count of less than 200/uL at the time of the first presentation to antiretroviral treatment (ART) clinics." (PMID 21356115, 2011). "This association remained significant after adjustment for other factors strongly influencing mortality: gender, nadir and zenith CD4 count, time with CD4 >500 cells/μl, most recent CD4 levels and AIDS diagnosis." (PMID 21789236, 2011). "Patients who first received cART in 1993-96 were much more likely to have previously received mono or duo ART than those who initiated cART in later time periods, and also initiated cART at lower CD4 counts and with more prior AIDS illnesses." (PMID 21345234, 2011). "Hence, it is conceivable that computation of the cumulative VL using more frequent measurements and/or single copy assays that assess VL below the detectable threshold of commercial assays might reveal that the cumulative VL is a more sensitive marker of not only AIDS risk but also CD4 recovery." (PMID 21625477, 2011). "We compared the data on distribution by CD4 count from the Kenya AIDS Indicator Survey (KAIS) with the model projection for 2007." (PMID 21490782, 2011). "The asymptomatic phase of HIV-1 infection is characterized by the progressive depletion of uninfected peripheral effector/memory (CD45RO+) CD4+ T cells that leads to subsequent immunodeficiency and AIDS symptoms." (PMID 21943198, 2011). "Very high viral load or extensively depleted CD4+ T cells in the acute phase often result in failure of immune control, and a fast progression to AIDS." (PMID 21359149, 2011). "In this study, HIV seropositive patients were mostly from middle age group (31-40 yrs) with CD4+ counts in majority of symptomatic AIDS patients below 200 cells/mm3." (PMID 21396133, 2011). "In the time period after first date with a CD4 cell count below 350 cells/μL or an AIDS defining event the adjusted RR for lung cancer was 1.48 (95% CI; 0.63 - 3.47)) compared to HIV patients with intact or restituted immune system." (PMID 21702995, 2011). "The asymptomatic phase of HIV-1 infection is characterized by a progressive depletion of uninfected peripheral effector/memory CD4+ T cells that subsequently leads to immune dysfunction and AIDS symptoms." (PMID 21943198, 2011). "The Δ32 CCR5 allele is associated with a reduction of the risk of all-cause mortality in HIV (+) patients alongside clinical and immunologic predictors such as AIDS, history of cART, lymphocyte CD4 cell count and gender." (PMID 21789236, 2011). "Next, the ability to predict progression to AIDS in this cohort using the DEM CD4 T cell phenotype was assessed." (PMID 21526194, 2011).
AIDS (continued). "Univariate analysis identified that a history of AIDS-related illness, HBV DNA >2,000 IU/ml, HBeAg positive status, CD4 count <200 cells/ml, and a nadir CD4 count <200 cells/ml were significantly associated with ALT elevation." (PMID 22069454, 2011). "In this study, HIV positive patients were mostly from middle age group,CD4+ counts in majority of symptomatic AIDS patients were below 200 cells/mm3." (PMID 21396133, 2011). "WHO HIV/AIDS clinical stage misclassification was minimised by use of experienced clinicians trained in the study protocols and blinding of the clinicians to the CD4 results." (PMID 21589912, 2011). "Patients with levels above 6% of CD4 T cells were more likely to progress to AIDS (log-rank P = 0.001, HR 0.336, 95% CI = 0.173–0.653)." (PMID 21526194, 2011). "In the Italian Cohort Naive Antiretrovirals, 26.1% of all HIV infected patients delayed initiating care for >6 months after HIV diagnosis, and these patients represented 26.1% of patients with <200 CD4 cells/mm3 or clinically defined AIDS upon enrolment." (PMID 21226905, 2011). "Such phases represent missed opportunities, as occurs when treatment is given to patients with CD4+ T cell counts ≤200 cells/mm3 or signs and symptoms of AIDS-defining illnesses." (PMID 21283618, 2011). "Univariate analysis factors modifying the risk of death included the CCR5 genotype, gender, history of cART, AIDS diagnosis and also CD4 lymphocyte nadir, zenith, the latest CD4 count and stable levels >500 cells/μl." (PMID 21789236, 2011). "Definitively determining the mechanism of CD4+ T cell depletion remains a central unresolved issue in AIDS research." (PMID 22096538, 2011). "A person is said to have full-blown AIDS when his/her CD4+ T-cell count falls below CD4crit+, typically around of 50 cells/μL." (PMID 21687584, 2011). "The WHO clinical guidelines for HIV/AIDS are widely used in resource limited settings to represent the gold standard of CD4 counts for antiviral therapy initiation." (PMID 21589912, 2011). "Over the long term, initiating HAART in patients with a higher CD4 cell count is likely to effectively control AIDS treatment expenses on ADEs and OIs, but some factors should be generally balanced when initiating HAART." (PMID 21241494, 2011). "The mean CD4+ T lymphocyte counts was 31.7 ± 38.6 cells/μl in 23 AIDS patients with cytomegalovirus retinitis." (PMID 22115120, 2011). "The proportion of late presenters (AIDS-defining clinical event or CD4 < 200/μL) across the entire study period (2000-2009) was 28.7%." (PMID 22166160, 2011). "HIV infection in humans leads to a selective depletion of CD4+ T cells that culminates in immunodeficiency or AIDS." (PMID 21255440, 2011). "We should check their eyes routinely such as dilated fundus examination with an indirect ophthalmoscope in the AIDS patients with CD4+ T lymphocyte counts< 50 cells/μl." (PMID 22115120, 2011). "Over the long term, initiating HAART to patients with higher CD4 cell counts is likely to effectively control AIDS treatment expenses for ADEs and OIs, but it will also increase the treatment costs over a longer period of treatment." (PMID 21241494, 2011). "Cases: patients with PIR, defined as CD4 < 350 cells/mm3 (hazard ratio for AIDS or death of at least 8.5) and undetectable HIV viral load on HAART for at least one year." (PMID 22047047, 2011). "One of the main factors that led to defining the AIDS as new clinical entity was the facility available to measure the ratio of helper (CD4+) to suppressor (CD8+) T lymphocytes." (PMID 21245613, 2010). "Continued excessive drinking can exacerbate the new liability from HIV infection, especially in those who develop an AIDS-defining event, such as severely low numbers of immune cells (i.e., CD4+ T-cell count under 200/mm3) targeted by HIV infection." (PMID 23584066, 2010).
AIDS (continued). "Cryptosporidium is a protozoan parasite which causes a self-limited diarrhoeal illness in immunocompetent individuals and chronic, intractable diarrhea in AIDS patients; especially those with a CD4 count < 100/ul." (PMID 21029408, 2010). "Most HIV-infected individuals in developing countries present for HIV/AIDS care and treatment late in disease progression, with very low CD4 counts." (PMID 20586959, 2010). "AVL-HIV/AIDS patients in clinical remission showed significantly (p < 0.001) lower numbers of CD4+ T lymphocytes in comparison to HIV-1 infected patients without leishmaniasis." (PMID 21171992, 2010). "Infected individuals usually begin Highly Active Anti-Retroviral Treatment (HAART) when CD4+ concentration levels drop into the range of 200 to 300 CD4+ cells per μL and are diagnosed as having AIDS when these counts fall below 200 CD4+ cells per μL." (PMID 22219687, 2010). "The number of CD4 cells in the blood is a strong predictor of the likelihood of AIDS or death in untreated HIV-positive individuals and in people starting cART." (PMID 20186270, 2010). "HIV/AIDS variables, such as CD4 T-cell count and HIV RNA level, play a secondary role for the prognosis of critically ill HIV/AIDS patients." (PMID 20698966, 2010). "All AIDS patients were found to have highly inverted ratio of CD4+ to CD8+ T lymphocytes indicating marked immunosuppression." (PMID 21245613, 2010). "The results show that the OFRR achieves accurate CD4+ and CD8+ counts at levels associated with HIV infection and the medically accepted levels to begin HAART and the AIDS threshold." (PMID 22219687, 2010). "Cys55 is next to Nef motif A56W57L58, a site important for Nef-CD4 interaction and development of AIDS." (PMID 20659345, 2010). "They calculated a pre-cART CD4 cell count slope from these counts and used statistical methods to investigate whether there was an association between the rate of decline in CD4 cell count and the time from initiating cART to the primary outcome—a first new AIDS-defining event or death." (PMID 20186270, 2010). "In the present study, we evaluated detection of IBD serological markers in AIDS patients with low CD4 counts (<300 cells/μl) and high plasma LPS levels." (PMID 21125014, 2010). "Sensitivity analyses using alternative estimates of pre-cART CD4 cell slope gave consistent results in adjusted Cox models for the time to a new AIDS event or death, with p-values ranging from 0.24 to 0.88." (PMID 20186270, 2010). "Another limitation is the narrow selection criteria used to define the study cohort, limited to AIDS subjects with CD4 counts <300 cells/μl and high plasma LPS levels." (PMID 21125014, 2010). "The reported effects of CD4 cell slope in cART-naïve patients were significant but small—for example, an adjusted HR for progression to AIDS of 1.02 for each 10 cells/μl per year decline in CD4 cell slope." (PMID 20186270, 2010). "AIDS can be clinically defined when (i) condition in which CD4 + T-lymphocyte counts are <200 cells/μl of blood, (ii) presence of AIDS defining illnesses like HAD (HIV-associated dementia), HIV wasting syndrome, etc." (PMID 21180461, 2010). "Salivary gland enlargement, rampant caries, and leukoplakia revealed significant relationship with the degree of immunosuppression and CD4 count compared to other oral manifestations of AIDS." (PMID 23346337, 2010). "Data of CD4+ T cell counts and/or clinical status for all patients were examined, and only samples from individuals diagnosed with AIDS or having CD4+ T cell counts ≤ 200 cells/μl were included in the analysis." (PMID 20307309, 2010). "Coverage is defined as the proportion of the population in need receiving ART, where need is those with CD4<200 or with AIDS defining illness." (PMID 20594370, 2010).
AIDS (continued). "Of note, in untreated patients the rate of CD4 cell decline explains only 3% and 7% of the variability in the time to AIDS and death respectively, and there is only a weak correlation between an initial viral load and the subsequent rate of CD4 cell decline." (PMID 20186270, 2010). "Of the 44 HIV+ individuals, 22 (50%) were classified as non-AIDS and 22 as having AIDS: CD4 T-lymphocytes counts below 200 cells/μl and AIDS indicator conditions as specified in the CDC AIDS case definition criteria." (PMID 20626870, 2010). "In an unadjusted Cox model, the hazard ratio for AIDS or death was 0.99 (95% confidence interval [CI] 0.95–1.02) for each 10 cells/μl per year reduction in pre-cART CD4 cell decline." (PMID 20186270, 2010). "In this study, AVL/HIV-AIDS patients presented very low CD4+ T cell levels during remission of clinical symptoms after successful anti-leishmanial therapy and under HAART use." (PMID 21171992, 2010). "CD4 counts were obtained for 184 out of 190 AIDS patients at prior to ART including 29 HBsAg positive of which 25 had CD4 counts." (PMID 20843322, 2010). "It has been suggested that after CD4+ counts fall below the AIDS threshold CD8+ cell levels will begin to drop from an elevated level." (PMID 22219687, 2010). "Of these, 21,983 (32%) had a prior history of antiretroviral therapy or HIV-1 RNA results and 1,487 (2%) had an AIDS-defining diagnosis recorded more than 3 months prior to the first recorded CD4 count." (PMID 21159161, 2010). "Severity of illness, time since AIDS diagnosis, CD4 cell count, antiretroviral treatment, incidence of severe sepsis, and organ dysfunctions were registered." (PMID 20698966, 2010). "Persistent immune activation plays a central role in driving CD4 T cell depletion and progression to AIDS." (PMID 20657770, 2010). "CD4+ T cell counts and viral load levels of HIV-AIDS associated leishmaniasis patients (visceral or tegumentary) and HIV-1 infected control group." (PMID 21171992, 2010). "By contrast, ATL/HIV-AIDS patients in clinical remission had higher CD4+ T cell numbers and exhibited the lowest HIV plasma viral load." (PMID 21171992, 2010). "Starting treatment at higher CD4 counts reduced the probability of AIDS or death, with those starting before reaching a level of 450 cells/mm3 having the most benefit." (PMID 20205768, 2010). "Concordant with other studies, viral load was a predictor of VF and mortality and CD4 count was a predictor of immune reconstitution, AIDS events, and mortality." (PMID 20507622, 2010). "Prognostic strength of CD4 slope for the prediction of clinical outcomes occurring between 1994 and 1995 in 3,078 AIDS-free patients from the CASCADE collaboration with a CD4 cell count in 1993 and at least one prior CD4 cell count." (PMID 20186270, 2010). "No statistical difference was noted between the two groups regarding CD4 cell count, time since AIDS diagnosis, and HAART use." (PMID 20698966, 2010). "Majority of subjects presented with one or more AIDS related and/or AIDS defining illnesses at the time of first CD4 T cell count (3,068, 83.4%)." (PMID 20626905, 2010). "Certain authors have suggested that with progression from HIV to AIDS the number of circulating CD4+CD25hi Treg as a proportion of CD4 T cells increases but their function (which was measured by FOXP3 mRNA expression) decreases." (PMID 20668701, 2010). "Observational studies have identified the CD4 cell count and the history of AIDS as the strongest predictors of disease progression." (PMID 20565900, 2010). "Risk factors associated with AIDS events after HAART were younger age, male gender, lower CD4 count, and prior AIDS events." (PMID 20507622, 2010). "AIDS'87 is defined by diagnosis of an AIDS sequela, or “clinical” AIDS, therefore most patients are typically past the earlier CD4 cell count <200 stage." (PMID 20877624, 2010).